IL6 (interleukin 6)
Diseases named in the same sentence as IL6 in open-access papers (continued):
Sharing a sentence is not in itself a finding about the gene and the disease.
Insulin resistance (continued). "It has been known that elevated circulating levels of TNF-α and IL-6 in obese subjects play an important role in the development of insulin resistance." (PMID 23191980, 2012). "Relevantly, IL6 is also increased in serum of patients with NAFLD and is linked with insulin resistance." (PMID 22295101, 2012). "Adipose tissue is thought to directly exaggerate insulin resistance and to trigger inflammation by secreting adipokines such as IL-6 and TNF-α." (PMID 23155382, 2012). "Insulin resistance is associated with inflammatory factors such as tumor necrosis factor-α (TNF-α) and interleukin-6 (IL-6) in T2DM patients." (PMID 22548048, 2012). "Serum cortisol levels also appear to be the best predictor for insulin resistance followed by interleukin-6 (IL-6) in persons with inflammatory conditions." (PMID 24052871, 2012). "Insulin resistance seems to be associated with a predominantly Th1 cytokine pattern: TNF-α (and to a lesser extent IL-1 and IL-6), produced by visceral fat among others, inhibits insulin signaling pathways, leading to insulin resistance." (PMID 23204981, 2012). "Adipokines, e.g. TNFα, IL-6 and leptin increase insulin resistance, and consequent hyperinsulinaemia influences breast cancer progression." (PMID 21774820, 2011). "Although IL-6 has been proposed to increase insulin resistance, the discovery that IL-6 is a myokine produced and released from skeletal muscle during exercise, led many to challenge this concept as insulin action is enhanced immediately after exercise." (PMID 21937762, 2011). "It was shown that at time of birth, infants born from obese women had increased adiposity, homeostasis model assessment of insulin resistance (HOMA-IR, a fasting index estimating insulin resistance), cord blood leptin and interleukin-6 (IL-6) concentrations." (PMID 22110473, 2011). "IL-6 is reported to induce insulin resistance in the liver, the skeletal muscle, and 3T3-L1 adipocytes." (PMID 22051061, 2011). "Increase in pro-inflammatory adipokines, such as TNF-α and IL-6, also leads to glucose intolerance and insulin resistance." (PMID 21569357, 2011). "Hyperinsulinemic-euglycemic clamp studies showed that IL-10 prevents IL-6-induced insulin resistance in the liver and the skeletal muscle in mice." (PMID 22051061, 2011). "Alternative explanations for peripheral insulin resistance in hyperthyroidism include an increased secretion of bioactive mediators (adipokines) such as interleukin 6 (IL6) and tumour necrosis factor a (TNFα) from adipose tissue in hyperthyroidism." (PMID 21941681, 2011). "Production of IL-6 increases with adiposity, and circulating IL-6 concentrations are highly correlated with percentage of body fat and insulin resistance." (PMID 21352586, 2011). "Circulating levels of IL-6 correlate with BMI, insulin resistance, and intolerance to carbohydrates." (PMID 21686173, 2011). "Apocynin administration suppressed the expression of these inflammatory agents, resulting in the reduction of circulating TNF-α, IL-6, and leptin levels that normally accompany insulin resistance." (PMID 21403905, 2010). "The activation of inflammation by the UPR also depends upon the IKK-NFκB pathway, also through IRE-1α, resulting in increased TNF-α and IL-6 production, further supporting its contribution to insulin resistance." (PMID 20706689, 2010). "TNF-α and IL-6 are known to promote lipolysis and the secretion of free fatty acids, which contributes to an increase in hepatic glucose production and insulin resistance." (PMID 20825686, 2010). "Since 2001 several population based studies have shown a positive correlation of IL-6 serum levels and insulin resistance in human subjects." (PMID 21179199, 2010). "Our primary outcomes are serum concentrations of leptin, adiponectin, TNF-α, C-reactive protein (CRP), IL-6 and insulin resistance." (PMID 20550712, 2010).
Insulin resistance (continued). "The expression of TNF-α, IL-6, MCP-1, and leptin is upregulated in the adipose tissue of obese mice which is closely associated with insulin resistance." (PMID 21403905, 2010). "The exact role of the opposite effects and clinical impact of p-TNF-α and p-IL-6 on development of insulin resistance and perhaps type 2 diabetes in subjects with unintentional wasting and women who gained body weight now needs to be examined further." (PMID 20529356, 2010). "In vitro studies demonstrated that chronic exposure to IL-6 induces insulin resistance in skeletal muscle through induction of JNK, SOCS-3, and protein tyrosine phosphatase 1B." (PMID 21197447, 2010). "NF-κB causes insulin resistance by stimulating proinflammatory cytokines like TNF-α, IL-6, IL-1β, and resistin, which in turn activates JNK and NF-κB pathways to create a vicious cycle that will exacerbate tissue damage." (PMID 20508722, 2010). "Our primary outcomes are serum concentrations of leptin, adiponectin, tumour necrosis factor-alpha, C-reactive protein and interleukin-6 as well as insulin resistance." (PMID 20550712, 2010). "In the present study we examined the effect of IL-6 inhibition on insulin resistance in human subjects with a rheumatoid disease." (PMID 21179199, 2010). "When compared to patients consuming a control diet, patients consuming a Mediterranean-style diet have significantly lower serum concentrations of high-sensitivity CRP, IL-6, IL-7, and IL-18 as well as a decreased insulin resistance." (PMID 20847813, 2010). "A strong link exists between increased inflammatory cytokines, such as tumor necrosis factor-alpha (TNF-α) and interleukin-6 (IL-6), and insulin resistance in obese individuals." (PMID 20877574, 2010). "Adipokines, such as tumor necrosis factor-α (TNF-α), interleukin-6 (IL-6), and adiponectin secreted from adipocytes and immune cells are predictors of vascular disease and insulin resistance." (PMID 20490354, 2010). "IL-6 controls the hepatic production of CRP, which is a risk factor for insulin resistance, breast cancer and cardiovascular diseases." (PMID 19545451, 2009). "Testing the relevance of each parameter to predict insulin resistance we found best performance for serum cortisol followed by serum IL6, leptin and adiponectin." (PMID 19087258, 2008). "Serum cortisol levels are the best predictor for inflammatory insulin resistance followed by IL6, leptin and adiponectin." (PMID 19087258, 2008). "Invitro studies demonstrate that IL-6 can induce insulin resistance inisolated 3T3-L1 adipocytes and in mice." (PMID 19148295, 2008). "Model assessment identified cortisol as the best predictor of insulin resistance, followed by IL6, leptin and adiponectin." (PMID 19087258, 2008). "Our study argues for a relevant role of IL6 as a mediator of stress dependent insulin resistance in the acute inflammatory setting in humans." (PMID 19087258, 2008). "Nevertheless, human and experimental animal studies do suggest that IL-6 is involved in the development of insulin resistance in adipose tissue, skeletal muscle, and particularly in hepatocytes." (PMID 19936194, 2008). "Interventional studies, using acute or chronic application of IL6, confirmed its potential to induce insulin resistance, while antibody-neutralisation experiments of IL6 were found to do the opposite." (PMID 19087258, 2008). "It has been suggested that IL-6promotes insulin resistance due to the observation that plasma IL-6 is oftenelevated in patients with metabolic disease." (PMID 19148295, 2008). "Growing evidence suggests that IL-6 is not only produced by fat cells but is also capable of inducing insulin resistance in these cells." (PMID 17374166, 2007). "Despite some controversy regarding the potential role of IL-6 in insulin resistance, IL-6 has been shown to inhibit insulin signaling and insulin action in isolated hepatocytes." (PMID 16787541, 2006).
Insulin resistance (continued). "In the present cohort of unselected RA patients, IL-6 was more strongly associated with endothelial dysfunction than were CRP, erythrocyte sedimentation rate and insulin resistance." (PMID 15899050, 2005). "A complicating factor in untangling the cause-effect relationships underlying sarcopenia is the ability of IL-6, TNF-α, physical inactivity, abdominal obesity, and other factors to cause insulin resistance in the elderly." (PMID 15904534, 2005). "Patients with type 2 diabetes and insulin resistance, many of whom are obese, have elevated levels of several inflammatory markers, including IL-6, TNFα, and sTNFR2." (PMID 15578112, 2004). "For cardiometabolic outcomes, EX + IF reduced total cholesterol, triglycerides, low-density lipoprotein cholesterol, and interleukin-6; improved fasting blood glucose, fasting insulin, and homeostasis model assessment of insulin resistance (HOMA-IR); and modestly increased VO2max." (PMID 41883415, 2026). "A chronic excess body weight condition increases production of free fatty acids, cytokines such as TNF-α and IL-6, and leptin from adipose tissue, whereas it decreases adiponectin production, which together lead to the development of insulin resistance and chronic hyperinsulinemia." (PMID 41376649, 2026). "Enhancements in inflammatory and metabolic indicators, such as decreased TNF-α, IL-6, and insulin resistance, may facilitate ideal endometrial gene expression profiles associated with implantation, including integrins, HOXA10, IGFBP-1, and angiogenic pathways." (PMID 41596408, 2026). "Chemerin may appear to contribute to insulin resistance, while IL-6 and C-peptide may reflect compensatory immune and β-cell responses during pregnancy." (PMID 42077672, 2026). "Additionally, the JAK/STAT pathway, activated by IL-6, contributes to insulin resistance by inducing the expression of SOCS proteins, which inhibit insulin receptor signaling, impairing normal insulin function." (PMID 40004236, 2025). "TNF-alpha and IL-6 indirectly mediate lipolysis and increase hepatic fatty acid synthesis, and they are positively related to adiposity and are correlated with cardiovascular disease (CVD) risk factors and insulin resistance." (PMID 41441034, 2025). "In addition, insulin resistance promotes the production and secretion of pro-inflammatory adipokines, such as interleukin-6 (IL-6) and tumor necrosis factor-α (TNF-α)." (PMID 40290665, 2025). "Elevated levels of chronic inflammatory markers, such as serum interleukin (IL)-6, C-reactive protein (CRP), and tumor necrosis factor-alpha (TNF-α), are associated with lower HGS and physical function and with the development of DM and insulin resistance." (PMID 40283630, 2025). "Future studies should incorporate imaging data, inflammatory biomarkers (e.g., CRP, IL-6), or metabolic pathways (e.g., insulin resistance, oxidative stress) to investigate potential mechanisms through which WWI may influence PRISm." (PMID 40463466, 2025). "HCV also induces IL-1β and IL-6, which are well known for inducing insulin resistance." (PMID 41012578, 2025). "Notably, TNF-α inhibits insulin receptors, impairing the glucose uptake in peripheral tissues, while IL-6 contributes to insulin resistance by reducing adiponectin levels." (PMID 41284085, 2025). "Elevated IL-6 and TNF-α levels have been implicated in insulin resistance and chronic low-grade inflammation, which could exacerbate hyperglycemia and predispose women with GDM to developing T2DM postpartum." (PMID 40225013, 2025). "Dietary patterns directly affect metabolic and inflammatory status - for example, excess intake of saturated fats and refined sugars promotes obesity, insulin resistance, and dyslipidaemia, which in turn amplify pro-inflammatory cytokines such as IL-6 and TNF-α." (PMID 41280310, 2025). "It has been proposed that TNF- α, not IL-6, is the primary cause of insulin resistance and dyslipidemia and that IL-6 is its marker." (PMID 39817379, 2025).
Insulin resistance (continued). "Both markers may be key indicators of metabolic disorders, but their specific roles suggest that IL-6 may have greater clinical significance in managing dyslipidemia and insulin resistance in middle-aged women." (PMID 40137151, 2025). "In this study, the mortality group may have had higher IL-6 levels than the survival group, potentially leading to increased insulin resistance." (PMID 40431655, 2025). "The pro-inflammatory cytokine environment in IBD, involving molecules like TNF-α, IL-6, and IL-1β, appears to exacerbate insulin resistance, especially in older individuals who may already be more vulnerable to metabolic disturbances." (PMID 41007787, 2025). "The immune system’s pro-inflammatory environment in IBD, characterized by cytokine dysregulation (e.g., TNF-α, IL-6, IL-1β), may contribute to systemic inflammation, further exacerbating insulin resistance in older individuals." (PMID 41007787, 2025). "For example, insulin resistance can lead to increased infiltration of inflammatory cells in adipose tissue, which release pro-inflammatory cytokines such as tumor necrosis factor-alpha and interleukin-6, further promoting inflammation." (PMID 40983922, 2025). "While chronic IL6 elevation exacerbates insulin resistance, our data suggest context-dependent modulation where momordic acid’s stabilization of IL6 and AKT1 interactions may reconcile contradictory reports on cytokine function in metabolic regulation." (PMID 40283911, 2025). "Moreover, hyperglycemia and insulin resistance stimulate systemic inflammation by the release of pro-inflammatory cytokines such as interleukin-6 (IL-6) and tumor necrosis factor-alpha (TNF-α) aggravating vascular damage." (PMID 40114220, 2025). "Furthermore, IL6, IL1B, and TNF are pro-inflammatory cytokines, which are associated with insulin resistance and the development of chronic inflammation." (PMID 40699728, 2025). "Psoriasis and metabolic syndrome may exacerbate each other—adipose tissue inflammation and insulin resistance can worsen psoriasis, and psoriasis-related cytokines (like TNF-α and IL-6) can induce insulin resistance and dyslipidemia, creating a vicious cycle." (PMID 41112228, 2025). "Notably, proinflammatory cytokines such as interleukin (IL)‐6, IL‐1, and tumor necrosis factor‐α, known contributors to insulin resistance and endothelial dysfunction in metabolic syndrome, are also implicated in vitiligo pathogenesis." (PMID 39831416, 2025). "In conclusion, markers of inflammation and insulin resistance, including IL-6, Hs-CRP, fasting insulin, and HOMA-IR, were significantly associated with BMI-for-age categories, with obese children showing higher levels of both inflammation and insulin resistance." (PMID 40641901, 2025). "Inhibiting IL-6 with antibodies showed potential in improving insulin resistance and T2D." (PMID 41472730, 2025). "Moreover, insulin resistance, associated with a chronic inflammatory state mediated by cytokines such as IL1-beta and IL6, is linked to Alzheimer’s dementia and CoI." (PMID 41394161, 2025). "Elevated levels of interleukin-6 and TNF-α in obese individuals could increase insulin resistance and cardiovascular risk." (PMID 40166678, 2025). "It is well known that IL6 interferes with glucose uptake in insulin-dependent tissues, by inducing insulin resistance; therefore, it also interferes with lipolysis and oxidation of glucose and fatty acids, with a resultant loading of the adipocytes with nutrients." (PMID 40003433, 2025). "Hyperglycemia (HbA1c>7%) activates the NLRP3 inflammasome, leading to increased IL-6 secretion from monocytes, reduced efficiency of serum albumin synthesis, and a positive correlation between the homeostasis model assessment of insulin resistance (HOMA-IR) and NLR." (PMID 40831574, 2025). "IL6, MMP9, and LOX1 have been linked to inflammation, insulin resistance, or arteriosclerosis." (PMID 40498722, 2025).
Insulin resistance (continued). "While IL-6 contributes to insulin resistance and chronic inflammation." (PMID 40385768, 2025). "Tnf is a tumor necrosis factor and it has been demonstrated that short exposures to PM2.5 significantly increase liver inflammatory factors including Il-6 and Tnf-α in rats, while the activation of inflammatory factors has been shown to contribute to insulin resistance." (PMID 40863931, 2025). "VAT functions as an endocrine organ, releasing proinflammatory cytokines (e.g., TNF-α and IL-6) and free fatty acids that mechanistically contribute to insulin resistance and oxidative stress through dysregulation of glucose homeostasis and mitochondrial dysfunction." (PMID 40702394, 2025). "First, insulin resistance promotes neuroinflammation, characterized by chronic low‐grade inflammatory responses, elevating pro‐inflammatory cytokines (such as interleukin‐6 [IL‐6] and tumor necrosis factor alpha [TNF‐α]), which impair neuroplasticity and enhance neuronal vulnerability." (PMID 41024619, 2025). "Despite the lack of association with metabolic syndrome as a whole, IL-6 shows stronger relationships with specific components of the syndrome, such as dyslipidemia and insulin resistance." (PMID 40137151, 2025). "Specifically, adipose tissue, especially visceral fat, secretes pro-inflammatory cytokines like tumor necrosis factor-alpha (TNF-α) and interleukin-6 (IL-6), which contribute to insulin resistance and may facilitate tumorigenesis in colorectal tissues." (PMID 40686812, 2025). "The relationship between insulin resistance and IL-6 levels was examined through linear regression." (PMID 40226143, 2025). "Studies have shown that aldosterone treatment of cultured adipocytes increases the expression of interleukin-6 (IL-6), plasminogen activator inhibitor-1, chemerin, and leptin, which are key players in the inflammatory cascade that can lead to insulin resistance." (PMID 39996060, 2025). "The increased fat mass is responsible for the production of inflammatory markers, such as tumor necrosis factor-alpha (TNF-α), interleukin-6 (IL-6), and other adipokines, which not only exacerbate insulin resistance but also have a direct catabolic effect on muscles." (PMID 40218995, 2025). "Additionally, TNF-α and IL-6 contribute to hepatic insulin resistance through upregulation of Suppressor of Cytokine Signaling 3 (SOCS3)." (PMID 41472723, 2025). "In addition, DNJ has anti-inflammatory and antioxidant activities, DNJ treatment reduced the levels of interleukin-6 (IL-6), tumor necrosis factor-α (TNF-α), and lipopolysaccharide (LPS) associated with insulin resistance." (PMID 40362022, 2025). "Third, although all analyses were multivariable-adjusted, many important potential confounders were not uniformly included across cohorts, such as inflammatory markers (hs-CRP, IL-6), renal function (eGFR), insulin resistance/HOMA-IR, depression, socioeconomic status, and physical activity levels." (PMID 41375847, 2025). "IL-6 may induce insulin resistance and increase the production of CRP in the liver by suppressing the expression of the insulin-sensitive glucose transporter in peripheral tissues." (PMID 40292283, 2025). "Additionally, genera, including Rothia, negatively correlated with IL-6 or insulin resistance showed a relative increase in the PCA and EU group, and these gut microbiota were positively correlated with IgG or IgM." (PMID 41227496, 2025). "IL-6 trans-signaling is crucial in intestinal dysbiosis, where alterations in the microbiota favor an increase in the levels of this cytokine, exacerbating systemic inflammation and contributing to insulin resistance." (PMID 40004236, 2025). "Studies suggest that in overweight or obese women, visceral adipocytes release inflammatory cytokines like tumor necrosis factor α (TNF-α) and interleukin 6 (IL-6), which contribute to insulin resistance and activate the inflammasome pathway, thus exacerbating PCOS symptoms." (PMID 41411269, 2025).